SNORA31 (small nucleolar RNA, H/ACA box 31)
Synonyms: ACA31; SNORA31A; IIAE10
Gene: Small nucleolar RNA gene on chromosome 13 (45,337,480 to 45,337,609, reverse strand). Ensembl gene ENSG00000199477.
Gene Ontology:
Biological process: RNA processing
Cellular component: nucleolus
Homologues: Orthologues: chimpanzee SNORA31 (100% identical), macaque SNORA31 (98% identical), pig SNORA31 (88% identical), rat Snora31 (87% identical), mouse Snora31 (85% identical), mouse Gm24165 (78% identical), mouse Gm24240 (52% identical). Paralogues in human: SNORA31B (72% identical).
Diseases named in the same sentence as SNORA31 in open-access papers:
SNORA31 is named in the same sentence as 9 diseases in open-access papers, as found by Europe PMC text mining. Sharing a sentence is not in itself a finding about the gene and the disease. The quoted sentences say what the papers report.
chronic myeloid leukemia (1 paper, 2021). "The expression of SNORA31 was markedly down-regulated in CD19+ b-cells of chronic myeloid leukemia (CLL) patients compared with normal B-cells." (PMID 34164339, 2021).
dystocia (1 paper, 2020). Slow or difficult obstetric labor or childbirth. "For metritis, the top associated variant, 3,662,486 bp on BTA4, is close to Small nucleolar RNA MBI-161 (SNORA31), and around ±1 Mb upstream and downstream were QTLs associated with production, reproduction, and dystocia." (PMID 31931710, 2020).
herpes simplex encephalitis (1 paper, 2023). Herpes simplex virus encephalitis (HSE) is caused by the infection of the central nervous system by Herpes simplex virus (HSV) that could have a devastating clinical course and a potentially fatal outcome particularly with delay or lack of treatment. "For example, SNORA31 variations impair cortical neuron-intrinsic immunity to herpes simplex virus-1 (HSV-1) and underlie herpes simplex encephalitis (HSE), thereby providing a new genetic aetiology and immunological mechanism of HSE." (PMID 38033868, 2023).
tumor (3 papers, 2013 to 2023). "Specifically, SNORA31 was significantly down-regulated in association with its host gene TPT1, which encodes for a critical protein involved in the control of stemness, pluripotency, or tumor reversion." (PMID 24004562, 2013).
SNORA31 also shares sentences with these, for which no sentence is quoted: cancer (3 papers); breast carcinoma (1); encephalitis (1); leukemia (1); lung carcinoma (1).